ALK (ALK receptor tyrosine kinase)
Diseases named in the same sentence as ALK in open-access papers (continued):
Sharing a sentence is not in itself a finding about the gene and the disease.
cancer (continued). "Grb2 was previously shown to be activated by ALK for cancer cell transformation and to interact with UVRAG, a regulator of the early stages of autophagy and autophagosomal maturation." (PMID 33452442, 2021). "In summary, our results indicate that ALK inhibition triggers LC3B-independent macroautophagic flux in EML4-ALK+ cells to support cancer cell survival and clonogenic growth." (PMID 33907223, 2021). "Since we previously published that the protein expression level of c-Myc is a key regulator of cancer stemness in ALK + ALCL26, we asked if experimental manipulations of c-Myc can modulate the SORE6 reporter activity." (PMID 34287231, 2021). "Mutations in the tyrosine kinase domain of Anaplastic lymphoma kinase (ALK) have also been identified in N.B. FDA approved a series of ALK tyrosine kinase inhibitors (TKIs) for use in ALK-driven cancers." (PMID 34943600, 2021). "Unfortunately, as observed for crizotinib, almost all cancer cells acquired resistance to second-generation ALK-TKIs." (PMID 33627640, 2021). "TKIs have been effective in targeting and treating cancers with specific anaplastic lymphoma kinase (ALK) rearrangements." (PMID 33802356, 2021). "Anaplastic lymphoma kinase (ALK) is an RTK that can be activated by mutations and acts as an oncogene in different cancers." (PMID 33407894, 2021). "A better understanding of the molecular biology and clinical aspects of cancers with ALK rearrangement is needed to determine the best treatment strategy." (PMID 34359604, 2021). "Since c-Myc was previously found to be a driver of cancer stemness in ALK + ALCL23, we also examined the expression and subcellular localization of this protein." (PMID 34287231, 2021). "The authors sought to outline ALK mutations linked to resistance to lorlatinib treatment by implementing N-ethyl-N-nitrosourea (ENU) mutagenesis screening of Ba/F3 models of ALK-positive cancer." (PMID 33572278, 2021). "Both entrectinib and crizotinib are popular approved drugs in inhibiting ALK tyrosine kinase for cancer prevention." (PMID 35356629, 2021). "Emergence of NGS-based approaches has boosted the potential use of liquid biopsies for mutation detection in several genes used as cancer biomarkers, such as EGFR and ALK, allowing the establishment of guidelines in targeted therapies using TKIs in NSCLC." (PMID 33916986, 2021). "Crizotinib is a dual inhibitor of MET and anaplastic lymphoma kinase (ALK) that has shown promise in multiple cancer types, including breast cancer." (PMID 34508101, 2021). "Repotrectinib shows high activity against ROS1/TRK/ALK fusion-positive cancers in preclinical studies." (PMID 34834176, 2021). "More than a decade later, subsequent work identified the ALK fusion proteins as oncogenic driver alterations in a variety of cancer types." (PMID 34446006, 2021). "Here we review recent findings in liquid biopsy technologies, including ctDNA, CTCs, exosomes, and other markers that can be investigated from plasma samples, in ALK-positive cancers." (PMID 34680298, 2021). "Immunohistochemical analyses of the cancer cell line (passage number 23) also showed ALK expression (ALK-positive) and confirmed thyroidal origin (TTF1 positive, PAX8 positive, thyroglobulin negative)." (PMID 33878728, 2021). "Oncogenes like MYCN and ALK result in increased replication stress in cancer cells, offering therapeutically exploitable options." (PMID 34819497, 2021). "CDK4/6is, Palbociclib, Ribociclib and Abemaciclib, have been effectively used in combination therapy, and have shown to be synergistic with drugs targeting other oncogenic pathways, including MEK, KRAS, BRAF, and ALK, in various cancers." (PMID 34138895, 2021). "In short, these new approaches are promising at more effectively overcoming and suppressing drug resistance, translating into more profound and more prolonged responses in patients with ALK-driven cancers." (PMID 34660278, 2021).
cancer (continued). "Alectinib has been shown to have high efficacy against crizotinib-resistant F1174L ALK-positive cancer cells." (PMID 34591871, 2021). "Translocations affecting the ALK gene lead to the expression of oncogenic ALK fusion proteins and increased cancer cell proliferation." (PMID 34832908, 2021). "Alectinib, crizotinib, ceritinib, brigatinib and lorlatinib for ALK-rearranged cancers, as well as dabrafenib and trametinib for BRAF V600 mutant disease." (PMID 32915318, 2021). "Anaplastic lymphoma kinase (ALK)-rearrangements are a key oncogenic driver, implicated in the pathogenesis of several human cancers." (PMID 33394101, 2021). "Entrectinib is an inhibitor of TRK, ROS1, and ALK, and has been shown to induce rapid and durable anti-cancer responses in NTRK, ROS1, and ALK-fusion tumors." (PMID 35126101, 2021). "PROTAC technology provides an ideal way to degrade ALK driver proteins to kill ALK mutant cancer cells and evade drug resistance." (PMID 34766150, 2021). "One of the clinical trials is an investigator-initiated, single-arm, open-label, phase II trial of alectinib for patients with ALK-positive rare cancers (JMA-IIA00364)." (PMID 34036223, 2021). "ALK+ NSCLCs are dependent on the activity of the fusion kinase, hence inhibition of ALK leads to the selective elimination of cancer cells." (PMID 34680298, 2021). "The strategy of treating ALK positive cancer with ALK‐specific PROTAC molecules provides another good opportunity to overcome drug resistance problems." (PMID 34766150, 2021). "Several ALK inhibitors have been developed for cancer therapy, and they have been classified as first-, second-, and third-generation ALK inhibitors." (PMID 34884690, 2021). "The ALK protein has been identified as a driver oncogene in diverse cancers, based on its overexpression after genetic translocation, amplification, or mutation." (PMID 33310759, 2021). "ALK signaling in cancer cells occurs by three main mechanisms: gene fusion, gene amplification and point mutations." (PMID 33916986, 2021). "These three ALK isoforms are expressed in approximately 2% to 3% of melanomas and sporadically in several other human cancers, such as lung adenocarcinoma and kidney renal clear cell carcinoma." (PMID 33466277, 2021). "Different gene rearrangements of anaplastic lymphocyte kinase (ALK) have been reported in several types of cancer, especially in NSCLC." (PMID 33692962, 2021). "Since then, many novel ALK partner proteins have been found and ALK has become a therapeutic target for cancer treatment." (PMID 34020009, 2021). "ALK has been described in a range of human cancers involved in cancer initiation and progression via activating multiple signaling pathways, such as the PI3K-AKT, CRKL-C3G, MEKK2/3-MEK5-ERK5, JAK-STAT and MAPK signaling pathways 19-23." (PMID 33391411, 2021). "As our in vitro studies demonstrated the potent antitumor activity of gilteritinib to ALK-rearranged cancer cells, we subsequently performed an in vivo study." (PMID 33627640, 2021). "A total of 33 adult patients with advanced cancers harboring genetic alterations in ALK including NSCLC participated in the study." (PMID 33394101, 2021). "Some showed superiority in killing ALK positive cancer cells and inhibiting the growth of cells expressing G1202R resistant ALK proteins comparing to inhibitor drugs." (PMID 34766150, 2021). "Based on the presented evidence, we believe that one of the mechanisms by which autophagy provides cytoprotective effects in ALK+ ALCL cells is related to its induction/maintenance of cancer stemness, which correlates with a high protein level of MYC." (PMID 34685497, 2021).
cancer (continued). "Many other ALK fusion proteins have since been described in different cancer forms, such as non‐small‐cell lung cancer, diffuse large B‐cell lymphoma (DLBCL) and inflammatory myofibroblastic tumour (IMT)." (PMID 33411331, 2021). "ALK autophosphorylation in these ALK-rearranged human cancer cell lines was also suppressed by gilteritinib." (PMID 33627640, 2021). "In view of our previous finding that c-Myc (another embryonic stem cell protein) can regulate cancer stemness in ALK + ALCL, we also asked if the expression level of c-Myc can regulate the SORE6 activity in these cells." (PMID 34287231, 2021). "Treating ALK mutant cancer patients with targeted therapy greatly reduces toxic adverse effect and improves patients’ quality of life comparing to traditional chemotherapy." (PMID 34766150, 2021). "One case (intraductal carcinoma) displayed strong membranous expression of ALK in 100% of cells and was subsequently shown to be positive for ALK rearrangement by FISH analysis." (PMID 33237469, 2021). "We identified a potentially targetable novel ALK fusion in an intraductal carcinoma of minor salivary glands." (PMID 33237469, 2021). "In our study, we assessed not only the ALK rearrangement driving the cancer but also other somatic aberrations." (PMID 32290439, 2020). "Later on, more targeted drugs have been developed against well-recognized driver kinases activated in cancer due to KGFs, such as those involving ALK, RET, ROS1, NTRK or FGFR39." (PMID 33257674, 2020). "Another study showed that age is an independent factor in predicting the frequency of ALK-positive cancer." (PMID 33425389, 2020). "A positive correlation between the proportion of cancer cells in the tissue section and ALK RNA expression level (R3) was found (P < 0.05)." (PMID 32543087, 2020). "Here, we provide a timely review on the most updated laboratory and patient-related findings on ALK and immunity, which would grant us important insights for the development of novel ALK immunotherapies for ALK-altered cancers." (PMID 32059449, 2020). "Up till now, most of the oncogenic events of ALK are known to promote cellular proliferation and survival signaling in cancer models, including the activation of the PI3K, JAK/STAT, and MAPK pathways." (PMID 32059449, 2020). "Anaplastic lymphoma kinase (ALK) is a tyrosine kinase that is constitutively activated in certain types of cancers due to genetic abnormalities, such as chromosomal translocations, gene amplification, and point mutations." (PMID 32283823, 2020). "Among these alterations, ALK gene amplification (ALK-A) has been identified in various cancers such as ALCL, rhabdomyosarcoma, carcinoma of the esophagus, adult renal cell carcinoma and hepatocellular carcinoma." (PMID 32664698, 2020). "In most ALK-rearranged cancers, the actual extracellular portions are the fusion partners of ALK, while the ALK kinase domain usually resides intracellularly." (PMID 32059449, 2020). "ALK has been targeted with small molecule inhibitors for the treatment of different cancers, but absolute success remains elusive." (PMID 32344689, 2020). "When existing separately, activating EGFR mutations are well defined predictive effects of EGFR-TKIs in NSCLC cancer patients, and while coexisting with KRAS mutations and ALK or ROS1 gene rearrangements, the EGFR-TKIs are predicted to be resistant." (PMID 32770988, 2020). "In summary, our data indicate that ETV5 regulation by activated ALK is a conserved feature across different cancer and cell types." (PMID 31937834, 2020). "With the emerging immune-related findings in ALK-altered cancers, various preclinical and clinical efforts are ongoing to identify novel ALK-related immunotherapies with potentially better or more sustained therapeutic effects or even cure of these cancers." (PMID 32059449, 2020). "This in silico approach attempts to efficiently examine potential interactions of ALK aberrations and PD-L1 signaling in human cancers." (PMID 32059449, 2020).
cancer (continued). "The anticancer drug Dox and ALK-specific siRNA were co-loaded to construct Dox/siRNA/DNMs for chemo-gene synergetic cancer therapy." (PMID 32724469, 2020). "In an advanced stage of NSCLC, cancer tissues will be analyzed for targetable mutations such as EGFR and anaplastic lymphoma kinase (ALK) to apply an appropriate TKI." (PMID 33172112, 2020). "This landmark study lays an important foundation for vaccine-based therapy for ALK-positive cancers." (PMID 32059449, 2020). "The present results showed the activation of YAP1 by ALC using an evaluation of ALK-rearranged cancer cells that survived a treatment with ALC." (PMID 31900393, 2020). "Anaplastic lymphoma receptor kinase (ALK) alterations have been identified in several human cancers, including neuroblastoma, glioblastoma, lung cancer, anaplastic large cell lymphoma, and renal cell carcinoma." (PMID 32312912, 2020). "Current drug therapies for ALK-positive cancers are mainly precision treatments with ALK inhibitors (crizotinib, ceritinib, alectinib, brigatinib, lorlatinib)." (PMID 32059449, 2020). "ALK-mediated ATIC phosphorylation can rescue cancer cells from antifolate agents induced cell death." (PMID 33520699, 2020). "Currently, ongoing clinical trials are carefully examining the potential clinical benefits of PD-1/PD-L1 checkpoint inhibitors and their safety in patients with ALK-rearranged cancers." (PMID 32059449, 2020). "Mutations in epidermal growth factor receptor (EGFR), as well as rearrangement of ROS1 and anaplastic lymphoma kinase (ALK), are suggested as the first-line treatment for metastatic LC, which contribute a lot to cancer patient OS." (PMID 32104702, 2020). "We found that the translocation of NHERF1 happened to heparin-induced endogenous NHERF1 expression in ALK positive cancer cells." (PMID 32164629, 2020). "A total of 89 cases were ALK‐positive, and there was a relationship between the proportion of cancer cells in the samples and the ALK R3 level (P < 0.05)." (PMID 32543087, 2020). "Residing on the cell surface, oncogenic ALK protein has been recently examined as a potential CAR-T target for ALK-positive cancers." (PMID 32059449, 2020). "ALK-rearranged cancer cells can also transfer the resistance to anti-ALK TKIs by releasing EVs containing a subset of specific miRNAs." (PMID 31877735, 2019). "Crizotinib, a small molecule inhibitor of c-Met and ALK, is a Food and Drug Administration-approved drug with reported efficacy in the treatment of cancer." (PMID 31278140, 2019). "Recently, small-molecule inhibitors of ALK currently used to treat ALK fusion-positive NSCLC have entered clinical trials for ALK-positive NB and other ALK-positive paediatric cancers." (PMID 31088252, 2019). "A newer inhibitors, entrectinib (RXDX-101), is a ROS1, Pan-TRK, and ALK inhibitor with activity in multiple molecularly defined cancer indications." (PMID 30930778, 2019). "Cerivastatin, the rate‐limiting enzyme inhibitor of the mevalonate pathway, showed anti‐cancer activity against ALK‐TKI resistance in vitro/in vivo, accompanied by cytoplasmic retention and subsequent inactivation of transcriptional co‐regulator YAP." (PMID 31633304, 2019). "In conclusion, ICIs show limited effectiveness in treating ALK‐positive NSCLC even though this cancer exhibits high PD‐L1‐positive rates." (PMID 31509890, 2019). "In this sequential, open-label, phase 1 trial (NCT02048488), patients received doses of 30 mg, escalated to 480 mg every 24 hours (Q24h), followed by an expansion cohort of patients with ALK-positive cancers." (PMID 31217479, 2019). "Among various fusion genes involved in cancers, anaplastic lymphoma kinase (ALK) has been found fused to various genes in diverse cancers." (PMID 31278140, 2019). "Performing clinical studies to further support our findings is feasible because of the availability of IGF-IR and ALK inhibitors that have been already approved to be used in patients with different types of cancer." (PMID 31340850, 2019).
cancer (continued). "Most of the molecular-targeted drugs used in the treatment of NSCLC inhibit specific targets that induce cancer evolution [so-called “oncogenic drivers (i.e., EGFR mutation, ALK translocation, ROS1 translocation, and BRAF mutation)”]." (PMID 31049758, 2019). "Cancer cells use EVs to transfer oncogenic ALK to normal cell in the surrounding tumor microenvironment and confer resistance to neighboring drug-sensitive cancer cells, via activation of the MAPK pathway." (PMID 31877735, 2019). "Molecular analyses, such as EGFR mutational and ALK FISH tests, are required by patients with advanced NSCLC to guide the selection of anti-cancer drugs (EGFR tyrosine kinase or ALK inhibitors)." (PMID 30807604, 2019). "Here, we show that NUMB binds to anaplastic lymphoma kinase (ALK), a receptor tyrosine kinase aberrantly activated in several forms of cancer, and this interaction regulates the endocytosis and activity of ALK." (PMID 30726988, 2019). "We also found ASP3026, a second-generation ALK inhibitor that has been recently utilized in patients with ALK+ cancers, capable of overcoming the resistance to crizotinib-induced ALK mutants." (PMID 31340850, 2019). "ALK fusions usually occur in patients with advanced adenocarcinoma, and patients with early-stage cancer composed the main population in the cohort studied by Ting and colleagues." (PMID 31387567, 2019). "For the first time, the direct effect of 7-epi-clusianone on cancer proliferation targets including microtubules and ALK (C1156Y) was determined." (PMID 31816878, 2019). "Intense research efforts regarding cancer genomes have identified several oncogenic pathways important in human cancers, and have led to improved therapeutic outcomes for tumors with EGFR, ALK, and BRAF mutations." (PMID 31848373, 2019). "Such NSCLC patients, who typically are non-smokers with adenocarcinomas, have been treated with crizotinib in first line (for ALK-positive cancers only) and, once the tumors become crizotinib-resistant and relapse, with other TKI inhibitors such as ceritinib." (PMID 30940805, 2019). "The ALK gene is also involved in other types of childhood and adult cancers in which chromosomal rearrangements lead to fusion proteins with constitutive ALK kinase activity." (PMID 31452835, 2019). "ALK fusion proteins are known to activate various signaling pathways, such as the PI3K/AKT pathway and the MAPK pathways, and aberrant activation of these ALK fusion proteins promotes proliferation and survival in cancer cells." (PMID 31533238, 2019). "We conclude that (R)-crizotinib acts as a TKI that favors the induction of ICD in a variety of cancer cells, independently of their ALK status." (PMID 30940805, 2019). "The aberrantly activated ALK promotes tumorigenesis by activating various cancer-related signaling pathways, including the MAP kinase proliferation and PI3K survival pathways." (PMID 30726988, 2019). "ALK has received a great deal of attention as a promising therapeutic target for targeted cancer therapy and, as a result, enormous efforts have been devoted to developing ALK inhibitors." (PMID 31401883, 2019). "The purpose of this study was to establish novel therapeutic strategies to eradicate cancer cells in ALK-positive NSCLC patients." (PMID 29930762, 2018). "The initial approval in 2015 by the US FDA was for treating patients with ALK cancers for both locally advanced and metastatic NSCLCs who had disease progression on crizotinib." (PMID 30336782, 2018). "Because aberrant forms of ALK are related to multiple cancers, understanding different aspects of this protein provides essential information for us to understand the role of ALK in diseases." (PMID 30400214, 2018). "The limited expression of ALK in immune-privileged sites and the central role of ALK fusion proteins in the development and maintenance of ALCL suggest that ALK has the potential to serve as an attractive target for cancer immunotherapy." (PMID 29642597, 2018).